C1GALT1 (core 1 synthase, glycoprotein-N-acetylgalactosamine 3-beta-galactosyltransferase 1)
Description:
Glycosyltransferase that generates the core 1 O-glycan Gal-beta1-3GalNAc-alpha1-Ser/Thr (T antigen), which is a precursor for many extended O-glycans in glycoproteins. Plays a central role in many processes, such as angiogenesis, thrombopoiesis and kidney homeostasis development (By similarity).
Synonyms: C1GALT; T-synthase
Tractability: Antibody: UniProt predicts a signal peptide or a membrane-spanning region. PROTAC: ubiquitination databases record sites on it.
Target class: Enzyme; Transferase
Gene: Protein-coding gene on chromosome 7 (7,156,934 to 7,248,616, forward strand). Ensembl gene ENSG00000106392.
Subcellular location: Membrane
Subcellular location (Human Protein Atlas): Cytosol; Nuclear bodies
Pathways (Reactome):
Disease: Defective C1GALT1C1 causes TNPS
Metabolism of proteins: O-linked glycosylation of mucins
Gene Ontology:
Molecular function: glycoprotein-N-acetylgalactosamine 3-beta-galactosyltransferase activity; protein binding; glycosyltransferase activity
Biological process: angiogenesis; kidney development
Cellular component: membrane; Golgi membrane
Genetic constraint (gnomAD): Loss-of-function variants: 12 observed, 32.99 expected, observed/expected ratio (o/e) 0.36, 90% interval 0.23 to 0.59. The upper end of that interval is the gene's LOEUF score, 0.59, which puts it in group 2 of 6, group 1 being the genes least tolerant of losing a copy. Missense variants: 415 observed, 437.6 expected, observed/expected ratio (o/e) 0.95, 90% interval 0.87 to 1.03. Synonymous variants: 173 observed, 147.68 expected, observed/expected ratio (o/e) 1.17, 90% interval 1.03 to 1.33.
Homologues: Orthologues: chimpanzee C1GALT1 (99% identical), macaque C1GALT1 (98% identical), dog C1GALT1 (93% identical), guinea pig C1galt1 (92% identical), rat C1galt1 (90% identical), mouse C1galt1 (89% identical), tropical clawed frog c1galt1 (72% identical), Caenorhabditis elegans C38H2.2 (45% identical), Drosophila melanogaster tgy (34% identical), Drosophila melanogaster CG18558 (33% identical), Drosophila melanogaster CG34057 (32% identical), Drosophila melanogaster CG2983 (28% identical). Paralogues in human: C1GALT1C1 (24% identical), C1GALT1C1L (21% identical).
Diseases named in the same sentence as C1GALT1 in open-access papers:
C1GALT1 is named in the same sentence as 68 diseases in open-access papers, as found by Europe PMC text mining. Sharing a sentence is not in itself a finding about the gene and the disease. The quoted sentences say what the papers report.
gastric cancer (16 papers, 2020 to 2025). A primary or metastatic malignant neoplasm involving the stomach. "Through the MAGMA tool based on GWAS data,C1GALT1 expression levels were associated with gastric cancer risk (P = 2.95 × 10−2, available online)." (PMID 38807485, 2024). "It has been reported thatC1galt1−/− mice are more susceptible to gastric cancer, and C1GALT1 expression affects gastric cancer progression." (PMID 38807485, 2024). "A similar observation was reported in gastric cells, in which loss of C1GALT1 activity is the cause of gastritis and gastric cancer by caspase-1/caspase-11 (Casp1/11)–dependent inflammasomes." (PMID 35207462, 2022). "In gastric cancer, increasing expression of C1GalT1 was associated with decreasing survival of patients over 60 months." (PMID 34944925, 2021). "Our findings open novel insights into the role of O-glycosylation in EPHA2 functions and highlight C1GALT1 as a potential diagnostic and therapeutic target for gastric cancer." (PMID 32005975, 2020). "C1GALT1 knockdown inhibits gastric cancer cell migration and invasion, which is associated with altered microtubule cytoskeleton organization." (PMID 32005975, 2020). "Noteworthily, the microtubule organization was also indicated to be related to lymph node metastasis, tumor stage, and poor outcomes of patients with gastric cancer, which are associated with C1GALT1 high expression." (PMID 32005975, 2020). "Core 1 synthase glycoprotein-N-acetylgalactosamine 3-β-galactosyltransferase 1 (C1GALT1) is known to play a critical role in the development of gastric cancer, but few studies have elucidated associations between genetic variants inC1GALT1 and gastric cancer risk." (PMID 38807485, 2024). "C1GALT1 over-expression—associated with tumor growth, metastasis, and poor prognosis—has been observed in various cancers—viz., ovarian cancer, head and neck cancer, hepatocellular carcinoma, breast cancer, colorectal cancer, and gastric cancer." (PMID 35207462, 2022). "In the present study, we found thatC1GALT1 expression was significantly correlated with the expression levels ofPD1 andPDL1, suggesting that C1GALT1 expression may be associated with immune infiltration and thus may play an important role in immune escape in the microenvironment of gastric cancer." (PMID 38807485, 2024). "The highest C1GalT1 median FPKM was seen in stomach cancer, and testis, pancreatic, and colorectal cancers were followed, respectively." (PMID 40548474, 2025). "For stomach cancer, normal tissues had a lower median of C1GALT1 gene expression level compared to tumor tissues (p = 0.00626 × 10−3)." (PMID 40548474, 2025). "In gastric cancer, C1GALT1 promotes EPHA2 phosphorylation and enhances soluble Ephrin A1-mediated migration mainly by modifying the O-glycosylation of EPHA2, thereby affecting the cell invasiveness of gastric cancer cells." (PMID 38699634, 2024). "On the contrary, ablation of C1GALT1 in gastric epithelium of mice induced spontaneous gastritis and gastric cancer and Tn antigen expression was related to tumor progression in gastric cancer patients." (PMID 36745330, 2023). "Recently, we suggested afzelin (kaempferol 3-O-α-L-rhamnopyranoside) as the structure suppressing glycosylation (e.g., by inhibition of C1GalT1, ST6GalNAcT, ST3GalT expression) in gastric cancer cells and in this way acting as a potential anti-cancer agent." (PMID 35955735, 2022). "Mice with knockdown of gastric epithelial C1GALT1 developed spontaneous chronic gastritis and gastric cancer." (PMID 35864552, 2022). "High expression of beta-1,3-galactosyltransferase C1GALT1 had been identified as an independent prognostic factor for worse overall survival in gastric cancer." (PMID 36110252, 2022). "SP1 knockdown was shown to decrease C1GalT1 expression while SP1 overexpression increase C1GalT1 expression in gastric cancer cells." (PMID 34944925, 2021).
gastric cancer (continued). "Consistent with our in vitro and in vivo data, these results suggest that C1GALT1 regulates the expression of genes related to several cancer malignant behaviors in gastric cancer cells." (PMID 32005975, 2020). "C1GALT1 knockdown, knockout, and overexpression in gastric cancer cells were confirmed by western blotting." (PMID 32005975, 2020). "To assess the effect of C1GALT1 on gastric cancer cells, we analyzed cell viability, migration, invasion, and chemoresistance using MTT, transwell migration, Matrigel invasion, and flow cytometry assays, respectively." (PMID 32005975, 2020). "We analyzed the expression of C1GALT1 in gastric cancers from tissue microarray and correlated these with clinicopathologic features and prognoses of gastric cancer." (PMID 32005975, 2020). "Knockdown or knockout of C1GALT1 inhibited malignant properties of gastric cancer cells in vitro and suppressed subcutaneous and peritoneal tumor growth in vivo." (PMID 32005975, 2020). "Our data consistently provide evidence that silencing C1GALT1 enhances the cytotoxicity of the chemotherapeutic drug 5-FU in gastric cancer cells through potentiating the apoptotic death response." (PMID 32005975, 2020). "We also found that the effect of C1GALT1 knockout on cell invasiveness and peritoneal tumor growth of gastric cancer cells was phenocopied by EPHA2 knockdown." (PMID 32005975, 2020). "Taken together, these results suggest that C1GALT1 promotes malignant behaviors of gastric cancer cells." (PMID 32005975, 2020). "Our study highlights the importance of GalNAc-type O-glycosylation in EPH receptor-regulated diseases and identifies C1GALT1 as a potential therapeutic target for gastric cancer." (PMID 32005975, 2020). "Elevated C1GALT1 levels have been observed in various cancers, including hepatocellular carcinoma, colorectal cancer, breast cancer, head and neck squamous cell carcinoma, prostate cancer, and gastric cancer." (PMID 39844613, 2025). "Similarly, the CREBBP gene was positively correlated with C1GALT1 gene expression levels in all cancer types, including pancreatic cancer, except stomach cancer." (PMID 40548474, 2025). "Similarly, in gastric cancer, the C1GalT1 gene and protein were significantly upregulated in tumor samples compared to healthy tissues, correlating with advanced disease stages and poor prognosis, consistent with our findings." (PMID 40548474, 2025). "On the one hand, C1GALT1 expression influences inflammatory and immune-mediated diseases; on the other hand, the immune microenvironment influences the treatment and prognosis of gastric cancer patients." (PMID 38807485, 2024). "Besides, C1GALT1 is able to modify O-linked glycosylation on integrin α5, thereby modulating activation of the PI3K/AKT pathway in gastric cancer cells." (PMID 38699634, 2024). "Both in vivo and in vitro experiments showed that C1GALT1 promotes EPHA2 phosphorylation and Ephrin A1-mediated cell migration by regulating the O-glycosylation of EPHA2, suggesting that C1GALT1 may be a potential therapeutic target for gastric cancer." (PMID 36429094, 2022). "On the other hand, the role of C1GALT1 in gastric cancer cannot be ignored." (PMID 36429094, 2022). "Next, we examined whether binding of Ephrin A1-Fc to surfaces of gastric cancer cells was affected by C1GALT1." (PMID 32005975, 2020). "Because altered glycosylation has been reported to modulate chemoresistance, we examined whether C1GALT1 could regulate 5-FU cytotoxicity in gastric cancer cells." (PMID 32005975, 2020). "Although the downstream signaling pathways of Ephrin A1-EPHA2 in gastric cancer cells remain unclear, the effects of C1GALT1 and EPHA2 on phosphorylation of these molecules, including EPHA2, STAT3, AKT, ERK, FAK, and Src, were similar." (PMID 32005975, 2020). "Moreover, we tested the effect of C1GALT1 knockout on peritoneal tumor growth because peritoneal dissemination is the most frequent metastatic pattern of gastric cancer." (PMID 32005975, 2020).
gastric cancer (continued). "Q-RT-PCR and western blotting showed variable C1GALT1 expression in five gastric cancer cell lines." (PMID 32005975, 2020). "We found that the expression ofC1GALT1 was positively correlated with the levels of infiltrating of CD4+ T cells and macrophages in gastric cancer, indicating that C1GALT1 may govern crosstalk with macrophages and cytotoxic T lymphocytes, which was consistent with those findings in a previous study." (PMID 38807485, 2024). "In gastric cancer AGS cells, suppression of C1GalT1 expression altered EphA2 O-glycosylation and reduced the EphA2 binding by its ligand Ephrin A1, resulting in deceased EphA2 phosphorylation and reduced cell migration and invasion." (PMID 34944925, 2021). "Binding of miR-181d-5q to the 3′UTR site of C1GalT1 indeed decreased C1GalT1 expression in lung cancer cells, while binding of miR-152 to the 3′UTR site on C1GalT1 reduced C1GalT1 expression in gastric cancer cells." (PMID 34944925, 2021). "The effects of C1GALT1 knockdown or knockout on cell invasiveness in vitro and in vivo were phenocopied by EPHA2 knockdown in gastric cancer cells." (PMID 32005975, 2020). "Silencing of C1GALT1 decreased tyrosine phosphorylation of EPHA2, inhibited binding of Ephrin A1 to cell surfaces, and suppressed soluble Ephrin A1-induced migration in gastric cancer cells." (PMID 32005975, 2020). "To further confirm that C1GALT1 mediated its pro-migratory effect at least partly through EPHA2, we analyzed EPHA2 phosphorylation and cell migration in C1GALT1 knockdown, EPHA2 knockdown, or double knockdown gastric cancer cells." (PMID 32005975, 2020). "In addition, the effects of C1GALT1 knockdown on cell invasiveness in vitro and in vivo were phenocopied by EPHA2 knockdown in gastric cancer cells." (PMID 32005975, 2020). "Although C1GALT1 is the critical O-glycosylating enzyme, its expression and role in RTK activities in gastric cancer remain unclear." (PMID 32005975, 2020).
colorectal cancer (15 papers, 2014 to 2025). A primary or metastatic malignant neoplasm that affects the colon or rectum. "The expression and mutation of Cosmc significantly impact C1GALT1 activity, levels, and Tn antigen expression, thereby playing a crucial role in the development of colorectal cancer." (PMID 38699634, 2024). "knocked out the gene encoding C1GALT1 in colorectal cancer cells, which prevented the expression of the T-synthase enzyme, leading to the expression of the Tn/STn antigen." (PMID 36686742, 2022). "Similar to our findings, increased C1GALT1(T‐synthase) and Cosmc expression levels were seen in an in vivo colorectal cancer study." (PMID 40548474, 2025). "The prospect of C1GALT1 in colorectal cancer (CRC) is multifaceted, mainly in terms of its key role in the process of tumorigenesis and progression as well as its potential as a potential therapeutic target." (PMID 38699634, 2024). "C1GALT1 plays a pivotal role in colorectal cancer (CRC) development and progression through its involvement in various molecular mechanisms." (PMID 38699634, 2024). "It has also been reported that C1galt1 plays an important role in the development and progression of colorectal cancer (CRC) by participating in various molecular mechanisms." (PMID 39767078, 2024). "A study revealed that the upregulation of C1GALT1 was accompanied by an increase in Cosmc levels in colorectal cancer cells." (PMID 38699634, 2024). "It has been reported previously that C1GalT1 is overexpressed in 67.5% of colorectal cancer patients." (PMID 37612278, 2023). "In colorectal cancer, patients with higher C1GalT1 expression were shown to have 20% poorer survival over 2000 days in comparison to those with lower C1GalT1 expression." (PMID 34944925, 2021). "We recently reported that C1GALT1 is up-regulated in colorectal cancer and hepatocellular carcinoma." (PMID 25762620, 2015). "Up-regulation of C1GALT1 enhanced malignant phenotypes in colorectal cancer and hepatocellular carcinoma through FGFR2 and MET signaling pathways, respectively." (PMID 25762620, 2015). "Previous studies have demonstrated, by quantitative real time RT-PCR, an overexpression of C1GALT1 in tumors of patients with colorectal cancer, promoting the invasive behavior of tumoral cells." (PMID 26500890, 2015). "Based on these findings and previous research on cancer, several hypotheses regarding the mechanism of C1GALT1 action in colorectal cancer (CRC) have been proposed." (PMID 38699634, 2024). "C1GALT1 produces tumor-associated carbohydrate antigens (TACA), such as Tn and sTn antigens, through the process of O-glycosylation, and these antigens have been associated with the spread of colorectal cancer and poor patient prognosis." (PMID 38699634, 2024). "Given the well-established significance of glycosylation in cancer, this article aims to review the role of C1GALT1 in the complex glycosylation process and its relationship with colorectal cancer, providing evidence for the identification of specific therapeutic targets for CRC." (PMID 38699634, 2024). "However, the knockout of C1GALT1 in colorectal cancer HCT 116 cells significantly promoted cell proliferation, adhesion, migration, invasion, and directly induced epithelial mesenchymal transformation (EMT) in colorectal cancer cells." (PMID 36429094, 2022). "A knockout of the C1GALT1 gene activated EMT process in human colorectal cancer cell line HCT116." (PMID 35892570, 2022). "Moreover, a Kaplan-Meier survival analysis showed that the cumulative survival rate of colorectal cancer patients with C1GALT1 overexpression (T > N) was significantly lower than the patients without C1GALT1 overexpression (T ≤ N)." (PMID 24758762, 2014). "Although it is widely accepted that O-glycans are highly expressed in colorectal tissues and changes in O-glycans may play significant roles in tumor progression, the expression and function of C1GALT1, a key enzyme for O-glycan biosynthesis, in colorectal cancer remain unknown." (PMID 24758762, 2014).
colorectal cancer (continued). "We found that inhibiting C1GALT1 expression was able to reduce sphere-forming ability of colon cancer cells, suggesting that targeting C1GALT1 may be a promising strategy to decrease cancer stem-like cells in colorectal cancer." (PMID 24758762, 2014). "An experiment has demonstrated that the inhibition of C1GALT1 is accompanied by an increase in the expression of sialic acid Tn and GSL-II binding (core 3 structure) in human colorectal cancer cells." (PMID 38699634, 2024). "Thus overexpression of C1GALT1 may reduce the core 3 structure, thereby inducing colorectal cancer." (PMID 38699634, 2024). "We previously found that C1GALT1 is overexpressed in hepatocellular carcinoma (HCC), colorectal cancer, and breast cancer." (PMID 29930379, 2018). "However, the role of C1GALT1 in colorectal cancer remains unclear." (PMID 24758762, 2014). "In other words, the impact of C1GALT1 on MUC1 glycosylation has a certain influence on the development of colorectal cancer, although the specific mechanism is not yet fully understood." (PMID 38699634, 2024). "Moreover, C1GALT1 regulates O-glycosylation of MET and FGFR2 in HCC and colorectal cancer cells, respectively." (PMID 29930379, 2018). "We recently reported that C1GALT1 alters O-glycan structures on MET and enhances MET dimerization in hepatocellular carcinoma; and C1GALT1 modifies O-glycans on FGFR2 and its downstream signaling involved in colorectal cancer malignant phenotypes." (PMID 25762620, 2015). "C1GALT1 expression was found to be overexpressed in colorectal cancer tissues compared with adjacent non-tumor tissues." (PMID 24758762, 2014). "Interestingly, the expression level of C1GALT1 is higher in SW620 cells than SW480 cells, which is in agreement with our hypothesis that C1GALT1 may enhance malignant behaviors of colorectal cancer." (PMID 24758762, 2014).